IL33 (interleukin 33)
Diseases named in the same sentence as IL33 in open-access papers (continued):
Sharing a sentence is not in itself a finding about the gene and the disease.
asthma (continued). "Finally, there is evidence in asthma that Treg cells are dysfunctional and though we saw only minimal effects of IL-33 on Treg (data not shown), our functional analysis was restricted to a small range of cytokines, and so this needs to be examined further." (PMID 30174671, 2018). "In summary, these findings suggest that the effects of IL-33 on the cellular response to RV differ in asthmatic and healthy individuals, thus providing a potential mechanism by which RV infection in a high IL-33 tissue microenvironment can induce immunopathology in asthma but not in healthy people." (PMID 30174671, 2018). "Furthermore, we found no deletions or duplications nominally associated with asthma symptoms in loci consistently associated with the disease in previous studies, including: DENND1B, IL1RL1, PDE4D, TSLP, IL13, HLA-DR/DQ and IL33 regions." (PMID 30262839, 2018). "Our data exclude that lung locally produced IL-33 could be important for the development of asthma, given that both mRNA and protein levels of IL-33 were not increased in animals." (PMID 28490737, 2017). "Indeed, IL-33 may be involved in human asthmatic disease, since it is increased in BALF of moderate asthma patients as compared to mild asthma patients or controls." (PMID 25849971, 2015). "Indeed, increased IL-33 levels were observed in the bronchoalveolar lavage fluid from subjects with moderate asthma compared with mild asthmatics and controls without asthma." (PMID 25061262, 2014). "Moreover, elevated levels of IL-33, IL-25 and/or TSLP were observed in the inflamed skin of patients with atopic dermatitis, in lung smooth muscle cells and epithelial cells from patients with asthma, and/or in sera from patients with AR." (PMID 24205109, 2013). "Given that many allergic reactions occur without a known allergen, including nonatopic asthma and idiopathic anaphylaxis 30, 34, IL-33 may play a critical role in these diseases." (PMID 22702477, 2012). "This activation in turn increased the production of IL-33, IL-25, and thymic stromal lymphopoietin (TSLP); raising the possibility that resident ILCs2 might be activated by these stroma-derived cytokines in HDM-induced asthma." (PMID 23209480, 2012). "Supporting this hypothesis, we have measured serum IL-33 levels in atopic and nonatopic patients with severe asthma by ELISA." (PMID 22702477, 2012). "IL-33 mediates its biologic effects via ST2, an IL-1 receptor-related protein specifically expressed on mast cells and Th2 lymphocytes that has been shown to function as an important effector molecule of Th2 responses in some experimental settings, including mouse asthma models." (PMID 20671916, 2010). "Notably, the administration of IL-33/ST2-neutralizing antibodies and PAD inhibitors (e.g., YW3-56) significantly attenuated MET release, suggesting that both the IL-33/ST2 signaling axis and PAD-dependent mechanisms represent promising therapeutic targets in asthma." (PMID 41008527, 2025). "Although we need to clarify the detailed mechanisms of the suppressive effects of kaempferol on IL-33-mediated activation of MCs, including the involvement of SHIP1 in this effect, kaempferol may be useful to prevent or treat IL-33-mediated allergic diseases such as asthma." (PMID 36983066, 2023). "Furthermore, to evaluate the effects of BMDCs on smoke-related asthma and to elucidate the underlying mechanisms by which CpG-ODN restores lung inflammation DC-related Th2/Th17 inflammatory response via IL-33/ST2 pathway, we did not perform CSE alone control in the current study." (PMID 36834541, 2023). "Anti-inflammatory and protective roles of IL-33 involved adaptive (Treg expansion) and innate immunity (ILC2 regulation), however activation of mast cells or eosinophils due to exaggerated IL-33 signaling, could also promote fibrosis and inflammation, such in asthma and autoimmunity." (PMID 36768322, 2023).
asthma (continued). "Furthermore, filaggrin deficiency could intensify the Th2 responses by induction of inflammatory molecules IL-33 and TSLP under the Th2 condition, which forms a positive feedback regulatory loop to amplify the immune response and promotes the progression of asthma." (PMID 34484176, 2021). "Considering the profound role of TLSP, IL-33, and IL-17A signaling in obstructive lung disease pathobiology, we sought to investigate whether the interactions between epithelium and macrophages impact TSLP, IL-33, and IL-17A expression in DCs in asthma and COPD." (PMID 32842623, 2020). "In a clinical study, rhinovirus infection increased IL-33 in the airway of asthma patients; even though this particular study also showed that rhinovirus increased IL-33 from bronchial epithelial cells in an ex vivo experiment, the true IL-33–producing cells in vivo was not identified." (PMID 31940364, 2020). "The specific cellular source of cytokine production in asthma is unclear, although evidence shows that allergens, including HDM, may activate airway epithelium leading to the release of mediators including IL-25, IL-33, and thymic stromal lymphopoietin, which activate ILC2." (PMID 30122959, 2018). "Thus, the asthma loci IL33, IL1RL1/IL18R1, RORA, and IL13 previously identified by GWAS belong to the same pathway, and could modify airway inflammation and interleukin responses that are crucial for the development of asthma." (PMID 23565190, 2013). "These cells have no impact on T-cells mediated allergen-induced asthma and therefore are not necessary for allergen-specific Th2 differentiation and IL-17RB+ lung-resident cells, probably nuocytes, that trigger Th2 responses in a manner dependent on IL-33 and/or IL-25." (PMID 23209480, 2012). "Moreover, PTGS1 may be activated by IL-33 to catalyze the production of PG, thereby activating the ERK signaling pathway, such as serine phosphorylation of phospholipase A2, initiating AA release and prostaglandin synthesis, and promoting the development of asthma." (PMID 41557720, 2026). "In conclusion, our findings indicate that in our study, IL-33 and TSLP are not biomarkers of mild asthma in children." (PMID 38731070, 2024). "Thirdly, the study did not explore IL‐33 levels in the airways (induced sputum, bronchoalveolar lavage (BAL) or other biological samples) in asthma." (PMID 37102668, 2023). "Paradoxically, COVID-19 patients with allergic asthma had more severe asthma presentation than those with nonallergic asthma, probably due to the enhanced ILC-2 response induced by IL-33 release." (PMID 37679779, 2023). "Probiotic and prebiotic treatments reduced the levels of Th2 cytokines (IL-4, IL-5, IL-13, IL-17, IL-25, and IL-33) and increased IFN-γ level in the BALF of asthmatic mice as compared to the non-treated asthma group." (PMID 35296330, 2022). "Thus, in mild asthma, the protection offered by epithelial-derived Type I IFNs towards MCs may outweigh the negative effect of IL-33 on ICAM1 expression and viral entry whereas in severe disease, a lack of epithelial IFNs may render the MCs more vulnerable to infection." (PMID 36366528, 2022). "In Korea, plasma IL-25, but not IL-33 or TSLP, was increased in patients with aspirin-exacerbated respiratory disease characterized by asthma, nasal polyps, and chronic eosinophilic sinusitis." (PMID 33945508, 2021). "In contrast, increased expression of IL-33 and TSLP, but not IL-25, was reported in asthma patients in London, Poland, and New York, New York." (PMID 33945508, 2021). "In severe asthma patients with CRS, there was an upregulated expression of IL-33, IL-25 and TSLP in their nasal tissues, compared to those in non-severe asthma patients." (PMID 28199345, 2017). "It is now also apparent that the downstream effector cells that are induced by IL-33, ILC2 cells are increased in the airways of children with severe asthma compared to non-asthmatic controls." (PMID 28725641, 2017).
asthma (continued). "The mRNA expression of TSLP, IL-25 and IL-33 was significantly higher in patients with severe asthma and CRS compared to those of non-severe asthma with CRS." (PMID 28199345, 2017). "Taken together, the data extend the list of asthma triggers that can induce ILC2 activation to include not only allergy and viral infection, but also O3, and IL-33 seems to be a common denominator inducing their activation in each instance." (PMID 27472835, 2017). "This is consistent with earlier reports in adult asthma, but contrasts with paediatric severe asthma in which neither epithelial nor ASM IL-33 expression was increased compared to controls." (PMID 25683166, 2015). "ILC2 have not been studied extensively in human asthma, though ILC2 as well as upstream cytokines and mediators including IL-33, leukotrienes, and PGD2 have been detected in human lungs." (PMID 24876829, 2013). "In parallel, IL-33/ST2-targeting agents, including ipeceximab (anti-IL-33), astegolimab (anti-ST2), and tozoracimab (anti-IL-33), are in late-stage development for asthma and COPD, with favourable safety profiles No oncology clinical trials of IL-33/ST2 blockade have yet been published." (PMID 41284319, 2025). "This study confirms proteostasis intermediates, chiefly HSP70, as chaperones for noncanonical IL-33 secretion and activity that may be amenable for therapeutic targeting in the chronic airway diseases COPD and asthma." (PMID 40553562, 2025). "Children with asthma had higher levels of IL-2 (p = 0.005), IL-5 (p < 0.001), IL-13 (p = 0.021), IL-17A (p < 0.001), IL-22 (p < 0.001), IL-33 (p < 0.001), TNF-α (p < 0.001), and lower levels of IL-10 (p = 0.046) and leptin (p < 0.001) compared to those without asthma." (PMID 39902293, 2024). "By inference, an increased role for the IL33/IL1RL1 signalling pathway may be present due to the increased abundance and therefore signalling response to these isoforms in some but not all asthma patients." (PMID 39301832, 2024). "LTRAs alone might increase inflammation and exacerbate asthma by inducing the production of IL-25, IL-33, and TSLP; therefore, LTRA monotherapy may not be an appropriate therapeutic option for asthma." (PMID 36674744, 2023). "Furthermore, exacerbated Th2 immune responses were observed in mice lacking SIGIRR in an OVA-induced asthma model, indicating that SIGIRR controls allergic inflammatory responses by suppressing IL33/ST2 signaling." (PMID 35011670, 2021). "In addition to collagen Iα1, IL-1α/β, but not IL-33, also suppressed the expression of the ECM proteins, periostin and fibronectin, which are known to be altered in expression in asthma." (PMID 32457454, 2020). "Mice lacking IL-1R failed to mount a Th2 immune response and did not develop asthma to HDM, IL-1α acted in an autocrine manner to trigger the release of DC-attracting chemokines, IL-33, and allergic sensitization to HDM was abolished in vivo when IL-1α was neutralized." (PMID 27046957, 2016). "We tested this hypothesis by comparing plasma cytokines, including IL-2, IL-5, IL-10, IL-13, IL-17A, IL-22, IL-33, IFN-γ, and TNF-α and the adipokine, leptin in normal weight and overweight/obese children, both with and without asthma in a cross-sectional study." (PMID 39902293, 2024). "Furthermore, no significant changes were observed in IL-33 levels across all GINA categories, which agrees with a recent study on TSLP and IL-33 serum levels in mild asthma patients, showing a slight reduction in sera in mild asthma compared to that in healthy controls." (PMID 38999286, 2024). "Moreover, IL-33 expression is not affected by steroid treatment in neonatal HDM-treated mice and in endobronchial tissues from children with severe therapy-resistant asthma." (PMID 30233590, 2018).
allergic disease (243 papers, 2011 to 2026). An immune response that occurs following re-exposure to an innocuous antigen, and that requires the presence of existing antibodies against that antigen. "In rodent experiments, IL-33 deficiency has been shown to cause an allergy-like reaction, demonstrating the efficacy of this cytokine in the adaptive immune response." (PMID 41596472, 2026). "IL-33, a nuclear cytokine, has been implicated in the pathogenesis of allergic diseases as a cytokine abundantly produced by various cell types, including epithelial and endothelial cells." (PMID 38731070, 2024). "Nuclear alarmins (TSLP, IL-33, IL-25) appear to have a critical role in IgE-mediated allergies but are also implicated in entities such as eosinophilic esophagitis." (PMID 37048784, 2023). "Cord blood IL-33 level was correlated to childhood allergy and associated with maternal DEHP exposure." (PMID 37545493, 2023). "Since its discovery, IL-33 has been implicated in the onset and progression of asthma, cardiovascular diseases, kidney injury, and allergic diseases, as well as in organ fibrosis." (PMID 37686309, 2023). "We evaluated the association of prenatal DEHP exposure and IL-33 in cord blood on the development of allergic diseases." (PMID 37545493, 2023). "IL-33 As an epithelial-derived cytokine, IL-33—a member of the IL-1 cytokine family—is implicated in allergy, autoimmunity, and inflammation." (PMID 37587450, 2023). "Apart from that, IL-33 was found to be associated with the IL-17 as well as IL-31 production in allergy-driven pathologies of allergic rhinitis." (PMID 36291105, 2022). "We additionally replicate the association of a previously reported rare (minor allele frequency < 1%) coding variant in IL33 and show significant enrichment of rare variant burden in genes from common variant allergic disease loci." (PMID 35368043, 2022). "IECs release cytokines, namely IL-33, IL-25, and TSLP (respectively encoded by Il33, Il25, and Tslp), that work as immune alarm signals in response to cellular stress or injury and are involved in the pathophysiology of allergic disease." (PMID 33803079, 2021). "Decreased vitamin D and increased IL-33 levels are also both associated to Th2 immunity in allergic inflammatory diseases, suggesting that they play contrasting roles in allergies." (PMID 33488605, 2020). "On the other hand, adaptive Th2 cells are also targets for IL‐33, which are the main drivers of allergy‐associated inflammation once individuals are exposed to the allergen." (PMID 32566227, 2020). "IL-33 has been implicated in the pathogenesis of a number of human diseases, including allergy, infection, inflammation, fibrosis, obesity, diabetes, and cancer." (PMID 32903501, 2020). "Oral supplementation with capsaicin was able to attenuate important factors associated to allergy such as inflammation and oxidative stress, resulting in lower IL-33 production in murine model of food allergy." (PMID 31316714, 2019). "Regarding the IL-33-ST2 axis in human allergic diseases, genome-wide association studies have clarified that a variety of SNPs in IL33 gene and IL1RL1 (ST2) gene are associated with asthma susceptibility." (PMID 30233590, 2018). "IL-33 is considered to be associated with the pathophysiology of several allergic diseases by regulating mast cells." (PMID 29691371, 2018). "Administration of IL-33 in mice causes massive tissue infiltration of eosinophils and elevations of typical type 2 cytokines such as IL-5, IL-9, and IL-13, contributing to allergy and fibrosis." (PMID 30483263, 2018). "The importance of IL-33 in allergic disease was initially identified through a genome-wide association study (GWAS)." (PMID 28721208, 2017). "In the Th2-mediated allergy, IL-33 plays a deleterious role associated with the activation and production of type II cytokines and AAM polarization." (PMID 28423665, 2017).
allergic disease (continued). "In this review, we will focus on the recent advancements in the field of IL-33 and its association with mast cells in the context of allergy and inflammation." (PMID 26425339, 2015). "Interleukin-33 is a unique cytokine that plays an essential role in regulating MC associated immune responses in allergic diseases." (PMID 26425339, 2015). "IL-33 and mast cells have been influentially associated to the pathophysiology of allergic diseases and inflammation." (PMID 26425339, 2015). "The levels of pro-inflammatory cytokines (IL-1β, IL-6, TNF), anti-inflammatory cytokine (IL-10), Th2-type cytokines associated with allergy (IL-4, IL-13, IL-33) and Th1-type cytokine (IFN-γ) were analysed from the treated skin sites of all groups." (PMID 25123235, 2014). "Interestingly, the expression of IL-13 and IL-33, anti-inflammatory cytokines associated with allergic diseases, was also statistically upregulated in the pdr6Δ-infected mice relative to WT." (PMID 40444466, 2025). "Interleukin-33 (IL-33) is considered to be a key factor in inducing Th2-type cytokine-associated immune responses, which plays an essential role in host defense against nematodes and allergic diseases." (PMID 39061526, 2024). "Interleukin-33 (IL-33) which belongs to the interleukin-1 (IL-1) family is an alarmin cytokine with critical roles in tissue homeostasis, pathogenic infection, inflammation, allergy and type 2 immunity." (PMID 37573373, 2023). "Individuals with this genetic variant tend to be at lower risk for other allergic diseases, showing that lowering IL-33 levels or partially blocking IL-33 function might be functionally useful." (PMID 34946955, 2021). "Cells that respond to TSLP and IL-33 include T-lymphocytes, type 2 innate lymphoid cells, eosinophils, neutrophils, basophils and mast cells, many of which are often associated with type 2 immune responses, such as allergies." (PMID 31275312, 2019). "Given the association of IL-33 with allergy, these observations suggest that the ability to release and process IL-33 may underpin the initiator role of protease allergens." (PMID 30423826, 2018). "This could reflect the different properties of IL-33 in regard to reported capacity to influence allergy associated models in comparison to Th1/Th17 dependent arthritis models." (PMID 28702024, 2017). "In addition to IL-9, IL-33 is also a crucial regulator of MC functions and both IL-33 and MC have been influentially associated to the pathophysiology of allergic diseases and inflammation." (PMID 28090087, 2017). "Interleukin-33 (IL-33), the most recently discovered member of the IL-1 superfamily, has been linked to several human pathologies including autoimmune diseases, sepsis, and allergy through its specific IL-1 receptor ST2." (PMID 27579324, 2016). "Immunoglobulin E, thymic stromal lymphopoietin (TSLP), and interleukin-33 (IL-33) may be implicated in the etiology of childhood allergy and are detectable at birth." (PMID 26084354, 2015). "IL-31 and IL-33 correlate with Th2-associated cytokines in allergic disease." (PMID 25061262, 2014). "In this scenario, we are able to hypothesize that IL-31 and the related IL-33 activity might be linked with vitamin D in allergic disease." (PMID 25061262, 2014). "We investigated whether low vitamin D is linked with circulating IL-31 and IL-33 in children with allergic disease of the airways." (PMID 25061262, 2014). "IL-33 is thereby thought to contribute to the development of Th2-cytokine-associated immune responses, including host defense against nematode infection and allergic diseases." (PMID 21494550, 2011). "In addition to, Nrf2-deficiency up-regulates IL-33 response and administrates allergy." (PMID 33743807, 2021). "It plays an important role in exacerbating inflammation in allergic diseases through eosinophil activation, with IL33 levels found to be elevated in patients with allergic airway diseases." (PMID 41332835, 2025).